SKA3 (spindle and kinetochore associated complex subunit 3)
Diseases named in the same sentence as SKA3 in open-access papers (continued):
Sharing a sentence is not in itself a finding about the gene and the disease.
pancreatic cancer (3 papers, 2020 to 2021). "High SKA3 expression is also related to tumor progression in cervical, colorectal, liver, and pancreatic cancers." (PMID 34572901, 2021). "Many studies have confirmed that SKA3 was upregulated in numerous cancers and act as an oncogene in cervical and pancreatic cancer." (PMID 34993016, 2021). "KEGG annotation showed the high SKA3 expression group participated in tumor-related signaling pathways (pancreatic cancer, pathways in cancer, toll-like receptor pathway, and adherens junction)." (PMID 33224872, 2020). "Our findings show that SKA3 may be involved in Wnt signaling, pancreatic cancer, pathways in cancer, toll-like receptor signaling pathway, and adherens junction, which are known to play a crucial role in tumor progression." (PMID 33224872, 2020). "We find that SKA1 and SKA3 expression correlates with prognosis and immune cell infiltration in PDAC, highlighting their potential as pancreatic cancer prognostic biomarkers." (PMID 33224872, 2020). "Next, we explored whether DNA methylation status influenced gene expression in 185 pancreatic cancer samples by analyzing 11 and 15 CpG sites in the SKA1 and SKA3 DNA locus, respectively." (PMID 33224872, 2020).
renal cell carcinoma (3 papers, 2018 to 2019). "Another target gene, SKA3, was overexpressed in renal cell carcinoma and its aberrant expression was associated with cancer cell malignant phenotypes." (PMID 31052206, 2019).
bladder tumors (2 papers, 2021 to 2022). "This implies that prominent SKA3 expression promotes the proliferation and metastasis of bladder tumors, which may be tightly associated with immunosuppressive tumors." (PMID 35546682, 2022). "To investigate SKA3 expression in the various cellular compartments of bladder tumor tissues, we reanalyzed a public single-cell RNA sequencing (scRNA-seq) dataset performed on CD45-negative cells acquired from MIBC patients." (PMID 34572901, 2021). "For all three cohorts, SKA3 was significantly upregulated in bladder tumors compared with normal bladder tissues." (PMID 34572901, 2021). "In addition, we utilized TIMER to investigate the relationship between SKA3 and immune infiltration in bladder tumor microenvironments." (PMID 35546682, 2022). "Subsequent functional studies on SKA3 in bladder tumors may help detect other novel therapeutic targets as well." (PMID 34572901, 2021).
head and neck cancer (2 papers, 2019 to 2020). A primary or metastatic malignant neoplasm affecting the head and neck. "Analysis of single-cell transcriptomic data also confirmed that PLK1 expression was positively correlated with SKA3 levels in head and neck cancer (GEO accession number: GSE103322)." (PMID 33106477, 2020).
leukemia (2 papers, 2013 to 2021). A malignant (clonal) hematologic disorder, involving hematopoietic stem cells and characterized by the presence of primitive or atypical myeloid or lymphoid cells in the bone marrow and the blood. "Elevated levels of SKA3 (red) were observed in breast, rectal, ovarian, bladder, lung, and leukemia." (PMID 34993016, 2021).
lymph node metastasis (2 papers, 2020). "SKA3 mRNA expression across LUAD tissue positively correlated with the occurrence of lymph node metastasis." (PMID 32068236, 2020). "The upregulation of SKA3 was mildly correlated with poor differentiation (P = 0.052), cervical lymph-node metastasis (P = 0.051), and distant metastasis (P = 0.056)." (PMID 33106477, 2020). "Here, we found that SKA3 is overexpressed in LUAD and its expression correlates with lymph node metastasis and poor prognosis." (PMID 32068236, 2020).
medulloblastoma (2 papers, 2021 to 2023). A malignant, invasive embryonal neoplasm arising from the cerebellum. "Two of these circRNAs, circular-spindle and kinetochore associated complex subunit 3 (circ-SKA3) and circ-DTL, promoted the malignant phenotype of medulloblastoma when upregulated." (PMID 36899402, 2023). "CircRNAs have also been documented in medulloblastoma: two circRNAs (circ‐SKA3 and circ‐DTL) promoted the proliferation, migration, and invasion of medulloblastoma cells in vitro by regulating gene expression." (PMID 36899402, 2023). "circ-SKA3 and circ-DTL promote the proliferation, migration and invasion of medulloblastoma cells by regulating the expression of host genes." (PMID 34116651, 2021). "This shows that circ-SKA3 and circ-DTL have key carcinogenic effects in the occurrence and development of medulloblastoma." (PMID 34116651, 2021). "Significantly higher expression of circ-SKA3 has also been reported in medulloblastoma compared with normal tissues." (PMID 36899402, 2023).
adenoma (1 paper, 2016). A neoplasm arising from the epithelium. "Here, we further demonstrated that SKA3 protein was progressively up-regulated during progression from adenoma to carcinoma within individual patients." (PMID 27329586, 2016). "We confirmed that Aurora A, SKA3, and DSN1 proteins were up-regulated in the adenoma and carcinoma tissues." (PMID 27329586, 2016). "Among the identified candidate genes, AURKA, SKA3, and DSN1, which are involved in cell cycle transition, cell growth, and proliferation, were progressively up-regulated in paired non-neoplastic colon tissues, adenomas, and carcinomas." (PMID 27329586, 2016).
age (1 paper, 2020). A temporal measurement of the time period elapsed since an identifiable point in the life cycle of an organism. "A previous study showed that the incidence of age-related neurodegenerative diseases is consistent with a dramatic decline in the number and function of adult neural stem cells, while SKA3 is closely associated with age-related central nervous system diseases." (PMID 32528520, 2020).
glioblastoma (1 paper, 2022). The most malignant astrocytic tumor (WHO grade IV). "Meanwhile, SKA3 expression was higher in glioblastoma than in normal tissues, and it was verified that patients with high SKA3 expression have a shorter survival time." (PMID 35546682, 2022).
kidney cancer (1 paper, 2021). Primary or metastatic malignant neoplasm involving the kidney. "In addition, the mRNA levels of SKA1, SKA2, and SKA3 were significantly overexpressed in several other tumors, including breast, lung, colorectal, and kidney cancer." (PMID 35095717, 2021).
laryngeal carcinoma (1 paper, 2022). Carcinoma that arises from the laryngeal epithelium. "For instance, SKA3 was proved to be bound up with advanced stage in laryngeal cancer and determined as a novel marker which had a carcinogenic effect." (PMID 35140788, 2022).
lung squamous cell carcinoma (1 paper, 2022). "The mRNA expression of BIRC5, SHCBP1, CCNA2, SKA3, and GINS1 in LUAD and lung squamous cell carcinoma (LUSC) tissues were all significantly higher than that in normal tissues." (PMID 34806315, 2022).
metastasis (1 paper, 2022). The spread or migration of cancer cells from one part of the body (where they first appeared) to another. "High SKA3 expression was significantly correlated with Borrmann type, N stage, and peritoneal metastasis (all p < 0.05)." (PMID 35295342, 2022).
neuroblastoma (1 paper, 2024). Neuroblastoma (NB) is the most common solid, extracranial childhood tumor. "Upregulated mRNAs, including SKA3, PLOD2, VIPR2, and GGT5, are implicated in neuroblastoma." (PMID 38892402, 2024).
pancreatic adenocarcinoma (1 paper, 2024). "Furthermore, functional enrichment analysis and protein-protein interaction network were used to predict the biological significance of SKA3 in pancreatic adenocarcinoma (PAAD)." (PMID 38791174, 2024).
pancreatic ductal adenocarcinoma (1 paper, 2024). An infiltrating adenocarcinoma that arises from the epithelial cells of the pancreas. "Although its involvement in the pathogenesis of various cancer types has been reported, the potential clinicopathological significance of SKA3 in pancreatic ductal adenocarcinoma (PDAC) has not been fully elucidated." (PMID 38791174, 2024).
paraganglioma (1 paper, 2022). A benign or malignant neoplasm arising from paraganglia located along the sympathetic or parasympathetic nerves. "Additionally, except for pheochromocytoma and paraganglioma, dramatically high expression of SKA3 in tumor tissues was also discovered compared to that in normal tissues." (PMID 36439516, 2022).
skin cancer (1 paper, 2022). "Notably, SKA3 expression was significantly associated with seven kinds of cancers, including bladder, lung, ovarian, colorectal, breast, brain, and skin cancers." (PMID 35546682, 2022). "Additionally, using Prognoscan database, we affirmed that high SKA3 expression in tumor tissues is significantly connected with poor prognosis of patients with bladder, lung, ovarian, breast, brain, and skin cancers." (PMID 35546682, 2022).
triple-negative breast carcinoma (1 paper, 2021). An invasive breast carcinoma which is negative for expression of estrogen receptor (ER), progesterone receptor (PR), and human epidermal growth factor receptor 2 (HER2). "SKA3 was overexpressed in ER-negative, PR-negative, triple-negative breast cancer patients and decreased status." (PMID 34993016, 2021). "In all molecular subtypes, SKA3 was the highest expression in triple-negative breast cancer and the lowest expression in luminalA, which was consistent with the previous analysis of the TCGA database." (PMID 34993016, 2021). "Thus, we explore the Asian-specific group further in the TCGA data, the results showed that SKA3 was overexpressed in ER-negative, PR-negative, triple-negative breast cancer patients and decreased status, which was roughly corresponding with our results." (PMID 34993016, 2021).
cancer (29 papers, 2013 to 2026). A tumor composed of atypical neoplastic, often pleomorphic cells that invade other tissues. "Previous studies showed that SKA3 is aberrantly expressed in numerous tumors and thereby associated with cancer progression and poor prognosis of patients." (PMID 38791174, 2024). "A recent study showed that SKA3 is associated with patient outcome and aggressive disease development in several cancers." (PMID 30459531, 2018). "The SKA3 gene, which is located on chromosome 13q, is associated with mitosis and cancer development." (PMID 30459531, 2018). "Therefore, considering early molecular events observed during PDAC development, we chose spindle and kinetochore-associated complex subunit 3 (SKA3) involved in chromosome segregation to determine its clinical value in examined cancer." (PMID 38791174, 2024). "SKA3 overexpression has been linked to the occurrence of various cancers." (PMID 35546682, 2022). "Attempts to elucidate the role of the SKA3 in cancers other than PDAC have yielded several conclusions." (PMID 38791174, 2024). "TCGA and GSE107943 datasets showed that SKA3 was markedly upregulated in various types of cancers, including CCA (Supplementary 1A-C)." (PMID 37821935, 2023). "In different databases, prognostic disparities in SKA3 expression levels of various cancers result from the heterogeneity of material gathering methods and the latent mechanisms underlying distinct biological characteristics." (PMID 35546682, 2022). "We employed databases such as TIMER, GEPIA, UALCAN, PrognoScan, and Kaplan–Meier plotter for all-around assessment of SKA3 expression and its correlation with cancer patient prognosis." (PMID 35546682, 2022). "Based on our results, we employed TCGA data in TIMER to investigate SKA3 expression and its prognostic impact on various cancer types, demonstrating that SKA3 was highly expressed in 20 different tumors compared to normal tissues." (PMID 35546682, 2022). "As a result, SKA3 impact on cancer prognosis, progression, and treatment must be identified and proven urgently." (PMID 35546682, 2022). "Meanwhile, significant relationships between SKA3 and immune checkpoint gene expression in pan-cancer indicate that SKA3 plays a key function in regulating tumor immunology." (PMID 35546682, 2022). "Then, we explored the prognostic value of SKA3 in various kinds of carcinomas using two powerful databases." (PMID 35546682, 2022). "We used the Oncomine database to analyze the expression of the SKA3 gene in 20 types of malignant tumors." (PMID 34993016, 2021). "As expected, these changes were associated with alterations in the proportion of Ki67-positive cells, indicating that SKA3 sustained cancer cell proliferation in vivo." (PMID 33106477, 2020). "We found the expression of SKA3 mRNA was higher in CC tissue than in normal tissue in both the Biewenga Cervix database (p < 0.001) and the Pyeon Multi-cancer database (p < 0.001)." (PMID 30459531, 2018). "SKA3 protein was strongly expressed in several cancer lesions whereas it was rarely expressed in normal lesions." (PMID 29928475, 2018). "Spindle and kinetochore-associated complex subunit 3 (SKA3), located on chromosome 13q, was identified as a novel gene involved in promoting malignant transformation in cancers." (PMID 30459531, 2018). "Finally, especially due to the unique pathobiology of PDAC, performing in vitro experiments explaining the role of SKA3 in this cancer would be a valuable supplement to the obtained results." (PMID 38791174, 2024). "Recent studies showed that SKA3 plays a cancer-promoting role, not only by affecting the proliferation of tumor cells through regulating cell cycle checkpoints, but also by participating in a variety of cell biological functions to affect the occurrence and development of tumors." (PMID 35295342, 2022). "Studies have shown that SKA3 mediates the metastatic profile and outcome of several cancers." (PMID 32068236, 2020).
cancer (continued). "It has been shown that SKA3 mediates cancer development and progression." (PMID 32068236, 2020). "Previous studies have reported that SKA3 participates in cancer pathogenesis and progression." (PMID 30459531, 2018). "Some studies have shown that SKA3 participates in cancer development." (PMID 30459531, 2018). "Moreover, the study showed that the miR-455-3p/SKA3 axis contributed to cancer cell aggressiveness." (PMID 29928475, 2018). "Taken together, these results indicated that SKA3 promoted LUAD liver metastasis through metabolic reprogramming that enhanced glycolysis, enabling cancer cells to overcome hypoxic hepatic barriers and colonize the liver more efficiently." (PMID 41298345, 2025). "SKA3 is a member of the SKA complex, which was considered to participate in malignant transformation in cancers." (PMID 34845974, 2021). "Using SKA3 silencing approaches, we highlight that SKA3 acts as an oncogene through direct binding to EGFR, and the subsequent activation of pro-cancer signaling pathways to promote LUAD metastasis." (PMID 32068236, 2020). "To study the regulation of LUAD via SKA3, we examined its role(s) in EMT, a key process during cancer metastasis." (PMID 32068236, 2020). "Despite the differences in effect size, these results strongly suggest that SKA3 overexpression was important for overriding mitotic checkpoints in both CIN-high and CIN-stable cancer cells." (PMID 27329586, 2016). "SKA3 acts as an oncogene by directly binding to EGFR and promoting cancer metastasis." (PMID 34059086, 2021). "However, there are no studies on how SKA3 regulates tumor cell metabolism to promote cancer metastasis." (PMID 41298345, 2025). "SKA3 immunoreactivity was observed in the nucleolus and cytoplasm of both non-neoplastic epithelium and cancer cells, and SKA3 staining was obviously stronger in CC tissue than in normal tissue (score > 6, **p < 0.01), indicating that SKA3 may play an important role in CC development." (PMID 30459531, 2018).
tumor (29 papers, 2013 to 2025). "Previous studies demonstrated that SKA3 was strongly implicated in tumor development and progression." (PMID 37821935, 2023). "Research exhibited that SKA3 was somatically mutated in breast cancer, and its ectopic expression promoted tumor progression." (PMID 35546682, 2022). "We focused on spindle and kinetochore-associated complex subunits 1 and 3 (SKA1 and SKA3) because we recently reported that regulation of SKA1 by anti-tumor miR-10a-5p was involved in RCC pathogenesis." (PMID 29928475, 2018). "Moreover, SKA3 expression was positively associated with the infiltration levels of B cell, neutrophils, and tumor purity, while negatively associated with the infiltration of CD8 + T cells and macrophages (P < 0.05)." (PMID 34845974, 2021). "Tumor growth in SKA3 deficiency was slower than that in the control group." (PMID 31804459, 2019). "Based on these studies, we propose that SKA3 is a pivotal gene regulating tumor cell metabolism and serves as a potential promoter of LUAD metastasis." (PMID 41298345, 2025). "Knocking down SKA3 combined with HIF-1α inhibitors (PX-478) suppressed tumor cell glucose metabolic reprogramming, weakened hypoxia tolerance, and synergistically inhibited LUAD liver metastasis." (PMID 41298345, 2025). "The subcutaneous tumour formation experiment in mice showed that gemcitabine obviously decreased the volume and weight of the subcutaneous tumour, while SKA3 overexpression decreased the sensitivity of CCA cells to gemcitabine." (PMID 37821935, 2023). "Translocations in FOXO3/PDGFD and DDX10/SKA3 are interesting due to their possible role in tumor cell growth and survival." (PMID 36831263, 2023). "Previous studies have shown that SKA3 is closely related to the occurrence and development of tumours." (PMID 37821935, 2023). "SKA3 overexpression accelerated tumour growth, while these changes were partly reversed by PARP1 and HIF-1a knockdown." (PMID 37821935, 2023). "Further examination of the tumour removed from mice showed that gemcitabine enhanced cell necrosis, while SKA3 overexpression weakened its effect." (PMID 37821935, 2023). "We found that tumor growth was reduced in the SKA3 silenced group; the volume and weights of tumors derived from SKA3 silenced cells were smaller than those in the control group." (PMID 35295342, 2022). "Overall, the level of SKA3 expression in tumor tissue significantly increased than in normal tissue." (PMID 35546682, 2022). "We next established a subcutaneous tumor model and examined the effects of SKA3 knockdown on tumor growth." (PMID 35295342, 2022). "We next performed immunohistochemistry of 164 GC tumor samples and found that SKA3 and DUSP2 were mainly expressed in the cytoplasm and nucleus." (PMID 35295342, 2022). "The expression of SKA1 and SKA3 in tumor free group were lower than the group with tumor, as well as the patient with vascular invasion." (PMID 36439516, 2022). "In vitro, suppressing circ-SKA3 slowed cell proliferation, migration, and invasion while inhibiting xenograft tumor growth in vivo." (PMID 35883576, 2022). "In our study, the Oncomine and TCGA database were used to analyze the expression of SKA3 in tumor tissues and normal tissues." (PMID 34993016, 2021). "It comprises three proteins (Ska1, Ska2, and Ska3) with theorized roles in chromosomal instability and tumor development, and its overexpression has been widely reported in a variety of tumors." (PMID 34045512, 2021). "Significant levels of inhibition of in vivo and in vitro tumor proliferation and invasion result from the downregulation of SKA3." (PMID 31804459, 2019). "The results showed that SKA3 mRNA expression was enhanced substantially in tumor tissues compared with normal tissues (p=1.03E-53)." (PMID 33817174, 2019).